MGMT (O-6-methylguanine-DNA methyltransferase)
Diseases named in the same sentence as MGMT in open-access papers (continued):
Sharing a sentence is not in itself a finding about the gene and the disease.
tumor (continued). "Furthermore, cotreatment of tumours with O6-benzylguanine, another otherwise nontoxic inhibitor of MGMT, increases the sensitivity of MGMT positive cells towards temozolomide." (PMID 12569392, 2003). "Limitations include observed synergistic effects may be specific to certain cell lines, raising concerns about generalizability across different GBM tumor types including GBM tumor cells, organoids, and in vivo models with and without the H3K27M mutation and MGMT gene methylation." (PMID 40145650, 2025). "However, increased MGMT methylation in non-cancerous mucosa could also be found in cases with no methylation in tumor tissue." (PMID 40357388, 2025). "In fact, a median OS of 35 months in patients undergoing to 6 cycles of TMZ might be influenced by IDH mutation since none of the patients are reported to undergo to tumor treating fields; while a median OS of 23 months may be related with a high prevalence of MGMT methylated patients, for example." (PMID 38774410, 2024). "This could conceivably overpower the repair capacity of the base-excision repair (BER) system in tumoral tissue, which, in turn, might allow for better synergisms to take place between unrepaired DNA methyl adducts and RT, irrespective of the MGMT presence or MMR status of the tumor." (PMID 39022643, 2024). "Notably, MGMT promoter methylations were more prevalent in the pseudo-progression group, where initial scans suggest tumor growth but may not reflect true tumor recurrence." (PMID 38674026, 2024). "Together, these data suggest that, since the rate of MGMT promoter methylation drops sharply below a TERT promoter VAF of ~ 0.18 (i.e., ~ 35–40% tumor cellularity) for IDHwt GBM, cases with such low VAF may be at increased risk of false-negative MGMT promoter methylation results by pyrosequencing." (PMID 37919784, 2023). "In addition, we also noted a large intertumoral heterogeneity in tumor volumes, this may have impacted the lack of statistical significance in our H460 model, even though we noted a strong trend toward decreased MGMT and increased CRT efficacy by AMONs." (PMID 33850305, 2022). "Thus, 300 days of survival in the absence of any signs of disease, combined with a lack of detectable human Alu sequences, indicated to us that the impact of NEO212 might indeed have been curative—and independent of the MGMT status of the tumor cells." (PMID 36551551, 2022). "Moreover, contamination by non-neoplastic MGMT-expressing cells could result in false-positive tumor sample scoring." (PMID 36009577, 2022). "Likewise, MGMT expression was lower in HCC tumor specimens than in non-tumor specimens." (PMID 35723009, 2022). "Besides, the response to TMZ is highly dependent on the MGMT methylation status of the tumor, which could not be determined on this autopsied material." (PMID 34842805, 2021). "In addition, we confirmed that the MGMT promoter methylation was significantly (P = 0.0001) correlated with longer OS in IDH-mutant patients with GBM, independently of age, gender distribution, tumor type (primary or recurrent/secondary), and the extent of resection." (PMID 33628600, 2021). "However, whether tumor immunity can be affected by the methylation status of the MGMT promoter has, to our best knowledge, not been explored before." (PMID 33614641, 2021). "Due to the great histological complexity of the tumor and the PT tissue, we performed an unbiased stereometric analysis of histological samples by evaluating the cell density of both positive and negative cells for MGMT, BCRP1, and A2B5, as described in the Materials and Methods section." (PMID 33562724, 2021). "Interestingly, based on the clinical characteristics of GBM patients, tumor cells collected from the MGMT-negative patients were also sensitive to Bru treatment at 48h, indicating that Bru successfully inhibited the proliferation of TMZ-resistant human primary GBM cells (case No. 4, 8)." (PMID 34970146, 2021).
tumor (continued). "Moreover, the efficacy might be not related to the MGMT status, number of relapse or maximal diameter of tumor, which may be due to the small sample size and need to be confirmed in a large-scale study." (PMID 33634023, 2020). "Therefore, noninvasive and preoperative prediction of the MGMT genotype in patients with IDH1-wildtype GBM by using computational model is possible with the help of wavelet transform features or nonenhanced part of the tumor core (NET)-hit features." (PMID 32942564, 2020). "However, the prognostic significance of the immune checkpoint molecule T cell immunoglobulin mucin-3 (Tim-3) on tumor-infiltrating immune cells (TIICs) and O-6-methylguanine-DNA methyltransferase (MGMT) promoter methylation status has not yet been fully elucidated." (PMID 33041828, 2020). "Thus, not treating rGBM patients with TMZ may not be justified, or at least the tumor MGMT promoter methylation status requires re-evaluation before making a therapeutic decision." (PMID 30766509, 2019). "It is worth remembering that MGMT is a suicide enzyme, i.e., one TMZ-induced lesion is repaired by one MGMT molecule that is destroyed in the process; therefore, a theoretic strategy could be envisioned whereby MGMT is depleted from the tumor by metronomic treatment with an alkylating agent." (PMID 31505812, 2019). "High MGMT expression and abnormal MMR function are mechanistically linked to TMZ resistance in multiple tumor models, and elevated MGMT expression or lack of MGMT promoter hypermethylation in patient tumor specimens is associated with a worse outcome in patients with GBM treated with TMZ." (PMID 27384876, 2016). "However this biological cut-off would not take into account the complexity of GBM samples that may contain a variable number of non-neoplastic cells whose “unmethylated” MGMT DNA is extracted with that of tumor cells." (PMID 27542245, 2016). "Furthermore, in clinical samples, we could not find any correlation between MGMT expression and tumour recurrence." (PMID 24259277, 2013). "This could mean that MGMT methylation of the tumour is host-specific rather than tumour-specific." (PMID 20736948, 2010). "The relatively selective suppression of MGMT activity in mer+ MET-dependent tumour cells, in combination with the inability of such cells to proliferate in the absence of MET, may lead to the development of more effective treatment strategies for mer+ MET-dependent tumours." (PMID 9062396, 1997). "This dual-mode delivery led to robust MGMT knockdown and significantly enhanced TMZ sensitivity, resulting in marked tumor growth inhibition in vivo, without inducing neurotoxicity." (PMID 40725021, 2025). "Despite NCCN guidelines emphasizing the incorporation of tumor molecular analysis, a substantial proportion of GBM patients in the United States still do not undergo MGMT promoter testing." (PMID 39907975, 2025). "This study demonstrated significant differences between MGMT promoter methylated and non-methylated HGG in the peritumoral edema volume and total-tumor/edema ratio." (PMID 41476598, 2025). "The interplay mechanism between IDH, O-6-methylguanine-DNA methyltransferase (MGMT)-promoter methylation, and protein methyltransferase proteins-5 (PRMT5) activity, with tumor progression has never been described." (PMID 38827324, 2024). "While our “baseline” USC04 model (tumor cells lacking MGMT) is shown to respond to a single TMZ treatment and also benefits from adding TMZ to RT, the 2 MGMT-overexpressing models demonstrate no benefit." (PMID 39022643, 2024). "As patients with unmethylated MGMT tumors may be unresponsive to temozolomide, several alternative treatment modalities have been proposed for these patients which include fractionated radiotherapy, chemotherapy agents independent of MGMT repair, immunotherapy and tumor-treating fields." (PMID 39272871, 2024).
tumor (continued). "Independent of MGMT promoter methylation, OS is 20.5 months in newly diagnosed GBM with tumor-treating fields in addition to current standard therapy." (PMID 37047153, 2023). "These tumor biomarker subgroup assessments (IDH1 and MGMT) were not performed in the EF-11 study (non-comparable)." (PMID 36239858, 2022). "Although tumor CcO activity alone was not confirmed as a prognostic marker in patients GBM, the interaction between CcO and methylated MGMT promoter warrants further evaluation." (PMID 35088051, 2022). "As both MGMT and HIF-1α showed negative expression in all the tumor lesions, correlation analysis or difference comparison was not further performed." (PMID 36591483, 2022). "In contrast, both MGMT and HIF-1α had negative expression in all the tumor lesions of the 17 nude rats." (PMID 36591483, 2022). "No positive correlation was evidenced for OS or PFS with age, sex, and tumor localization (data not shown), PTEN, MGMT and EGFRvIII." (PMID 36499683, 2022). "The tumor progression in the TMZ group was the same as that of the control group, which was not surprising, as R2J-GS cells expressed MGMT." (PMID 34638987, 2021). "Data on the molecular tumor markers, particularly IDH, 1p19q, and MGMT promoter methylation, were not available for all patients." (PMID 34131646, 2021). "More evidence shows that CAFs are an independent prognostic factor and CAFs are enriched in patients with a poor survival rate, older age, high tumor grade, IDH wild-type, 1p/19q non-codeletion, and MGMT promoter unmethylation." (PMID 34778248, 2021). "Genetic analysis of primary tumour revealed KRAS Q61K, wild-type IDH1/2, H3F3A, HIST1H3B and TERT promoter, and no MGMT promoter hypermethylation." (PMID 34525976, 2021). "Cerebral magnesium was significantly higher in patients with MGMT methylation and no EGFR amplification in tumor and contralateral side (p < 0.0001)." (PMID 34298788, 2021). "All groups except for MGMT unmethylated, EGFR not amplified group had significantly lower PCr/Pi ratio in tumor voxels compared to contralateral voxels (p < 0.0001)." (PMID 34298788, 2021). "In hindgut NETs, a significantly negative or inverse correlation was detected between the MGMT or GLUT2 status and Ki-67 LI of tumor cells." (PMID 33287738, 2020). "In the present study, we demonstrate that NEO212 has superior tumor cell uptake and much better radiosensitization properties than TMZ at clinically relevant concentrations for GB and irrespective of MGMT or MMR status." (PMID 32881880, 2020). "FET-PET-based biological tumor volume in newly diagnosed GBM has been shown to be a prognostic imaging biomarker for survival, independent of MGMT promoter methylation." (PMID 33072586, 2020). "For the 5 patients with low tumor MGMT expression, 3 displayed a nuclear DDR biomarker response to treatment, whereas 1 did not and 1 was not assessable due to insufficient tumor tissue in the on-treatment biopsy." (PMID 33216844, 2020). "When surgery is not possible, the MGMT methylated status is proven to be a favorable marker for OS and PFS in patients with remnant tumor after an incomplete tumor resection (in both PR and biopsied patients)." (PMID 32039032, 2019). "Regardless of mechanism, the dual regulation of both MGMT and Ki67 by the K-M enhancer highlights the potential for this enhancer to influence both TMZ efficacy and tumor proliferation." (PMID 30054476, 2018). "For the remaining genes (SSBP2, MCAM, ERα, ERβ, CCND2, MGMT, GSTP1 and p16) methylation in serum DNA was always corresponding to methylation of tumor DNA, while methylation of tumor DNA was not always corresponding to methylation of serum DNA." (PMID 28147335, 2017). "The pre-treatment NLR did not vary significantly with sex, age, tumor size, KPS, degree of resection, BMI and MGMT promoter methylation status." (PMID 26341881, 2015). "High MGMT expression intensity was correlated with longer OS but not with DFS, tumor stage, or differentiation grade." (PMID 25015560, 2014).
tumor (continued). "In 15 tumours, the M/U ratio was 0 (no M primer MSP product detectable), indicating an unmethylated MGMT promoter status." (PMID 22428052, 2012). "Additionally, the tumor samples used were not microdissected, leaving open the possibility of contamination from surrounding normal tissue and stroma, although previous studies have demonstrated that MGMT is not generally methylated in normal head and neck tissue." (PMID 19807915, 2009). "When comparing patients with and those without available MGMT assessment, imbalances were noticed for the clinical characteristics age, MMSE score, extent of surgery and tumour location." (PMID 17609661, 2007). "At diagnosis (s = 0), 12-month survival estimates varied significantly with age >60 at diagnosis, preoperative tumor rim volume >20 cm3, absence of O6-methylguanine-DNA methyltransferase (MGMT) promoter methylation, postoperative KPS ≥70, residual postoperative tumor >1 cm3, or biopsy only." (PMID 41472359, 2025). "We examined a set of twenty adult GB patients, including individuals with and without O6-methylguanine-DNA methyltransferase (MGMT) methylation, to assess the similarities and distinctions between orthotopic murine tumours and the enhancing/non-enhancing central tumour regions in patients." (PMID 40282434, 2025). "Therefore, this study examined contrast enhancing tumor, central necrosis and peritumoral edema volumes using both automatic and manual segmentation methods, in HGG patients with and without MGMT promotor methylation." (PMID 41476598, 2025). "MGMT status could be used to recommend either lomustine or a rechallenge with TMZ in MGMT methylated patients, or re-mHSRT in non-methylated small tumours at disease progression." (PMID 39587462, 2024). "Nonetheless, using TMZ with other chemotherapies may decrease the sensitivity of the tumor cells to TMZ, regardless of MGMT-promoter status." (PMID 38827324, 2024). "Furthermore, DACH1 expression decreased significantly with increasing tumor grade, and it was also lower in patients with advanced age, IDH wild-type, and MGMT non-methylation." (PMID 36959804, 2023). "Importantly, the outcome of the patients remained independent of the size and location of the tumour, as well as its molecular characteristic (IDH and MGMT methylation); the only 2 significant factors were performance status and age." (PMID 37665387, 2023). "This is the first time, to the best of our knowledge, that a comparison has been made in one study of the effects of TMZ in a TMZ-responsive tumor model, i.e., U87MG and GL261 cells, and of non-responsive models related to their MGMT promotor methylation status, i.e., U118MG and U138MG cells." (PMID 37760448, 2023). "Although this outcome was not predicted by MGMT methylation status, it was consistent with OBSC data: our DSSs suggested that TMZ (DSS = 26) and XRad (DSS = 16) would show limited efficacy against this tumor." (PMID 37192626, 2023). "Similarly, those patients in which the tumor had high PROM1 expression and MGMT was methylated had a longer survival than unmethylated or patients with low expression of PROM1, regardless of MGMT methylation status." (PMID 36333778, 2022). "Although patients without neoplasia were selected, aberrant methylation of the CCNA1, DAPK, DCC and MGMT genes was present in the pretreatment oral rinse samples in all participants of both groups, an epigenetic event that is the target of action of valproic acid." (PMID 34385507, 2021). "Necrosis, tumor mass, and FLAIR-T2 volumes in non-methylated MGMT tumors were larger than in methylated MGMT tumors: 18.7 vs. 10.7 cm3, 33.9 vs. 23.3 cm3, and 104.3 vs. 82.1 cm3, respectively, without statistical significance (Mann–Whitney U-test p = 0.161, 0.204, and 0.195, respectively)." (PMID 32984040, 2020).
tumor (continued). "Promoter methylation levels of MLH1, MGMT, CDKN2A, and RASSF1A genes were not increased in cancer with respect to healthy tissues and did not correlate with the histological or pathological features of the tumor or with the MG symptoms." (PMID 33192293, 2020). "In MGMT promoter methylated GBMs, intraoperative ultrasound, intraoperative MRI, and 5-aminolevulinic acid (5-ALA) fluorescence staining can more accurately determine tumor boundaries, reduce the false-negative rate, and, ultimately, improve EOR." (PMID 32922947, 2020). "Bioluminescence images and IHC also revealed that Fstl1 silencing could not affect the tumor growth and the levels of cleaved caspase-3, γ-H2AX, and MGMT in DIP2A-KD P-GBM2 cells following TMZ treatment." (PMID 30542120, 2019). "In the last decade, many publications have explored resistance mechanisms to TMZ, including the tumor heterogeneity, MGMT (O-6-methylguanine-DNA methyltransferase), and mismatch repair status, but these processes have not completely explained this lack of sensitivity in pediatric patients." (PMID 31779235, 2019). "However, MGMT expression was found to not correlate with biological tumor behavior and TMZ treatment success in every case (positive response to TMZ in only 73% of MGMT negative cases)." (PMID 29344904, 2018). "The time to experience tumor progression was also significantly shorter in patients with high BICD1 expression (P=0.000321), while it was not significantly shorter in patients with high MGMT expression (P=0.469433)." (PMID 29371945, 2017). "Thus, the classification scheme showed prognostic value independent of tumor grade, IDH1/2 status, patient age and therapies (not independent of IDH1 status, age, MGMT promoter methylation and therapies in TCGA GBM samples)." (PMID 27323851, 2016). "The presence of a non-proliferating compartment in the tumor mass may limit the efficacy of TMZ as monotherapy even in the case of malignancies with functional MMR and low MGMT activity." (PMID 24593254, 2014). "MGMT, VGF, CCNA1 and FKBP4 are interesting, as they could be specific for tumours as all of the normal samples showed no methylation, and in addition, hMLH1 that had only one positive in normal." (PMID 22068818, 2012). "MGMT, an enzyme antagonized by TMZ, was negative in the tumor." (PMID 23091742, 2012). "In tumor tissue as compared to normal brain, DNMT1 andDNMT3b were significantly upregulated (DNMT1: 2.5-fold, DNMT3b: 3.2-fold, p<0.001); thedegree of upregulation did not correlate with MGMT promotermethylation status and MGMT mRNA expression." (PMID 21365007, 2011). "In addition, patients whose tumours had a methylated MGMT gene promoter benefited from TMZ, whereas those who did not have a methylated MGMT promoter derived no or only limited benefit from the addition of chemotherapy." (PMID 17609661, 2007). "Non-butterfly ccLGG, less tumor volume, genu invasion of CC (compared to splenium invasion), less volume of CC invasion, higher EOR, longer chemotherapy cycles of Temozolomide (TMZ), higher KPS on 3 months and MGMT methylation were positive factors for PFS of ccLGG." (PMID 42063089, 2026). "Interestingly, in the same study, tumor-related epilepsy at diagnosis also was a predictor of a more favorable survival independent of tumor location and volume, age, KPS score, extent of resection, radiochemotherapy, levetiracetam use and MGMT promotor methylation." (PMID 38730694, 2024). "However, following our procedure, some non-methylated tumor cases turned out to be nevertheless responsive to TMZ, suggesting that our approach could be synergistic with the classical MGMT methylation biomarker." (PMID 36132155, 2022). "However, those patients in which the tumor had high SOX2 expression and MGMT was methylated showed a longer survival than when unmethylated with high SOX2 expression, or patients with low expression of SOX2 regardless of MGMT methylation status." (PMID 36333778, 2022).